ROR2 (ROR family WNT receptor 2)
Diseases named in the same sentence as ROR2 in open-access papers (continued):
Sharing a sentence is not in itself a finding about the gene and the disease.
gastric cancer (11 papers, 2017 to 2024). A primary or metastatic malignant neoplasm involving the stomach. "The Wnt/PCP co-receptor ROR2 can be directly transferred from CAFs to gastric cancer cells, triggering JNK signaling, actin polarization, and directional migration in these cells." (PMID 39850884, 2024). "Here, we show that these cancer-associated fibroblasts provide both the signaling protein WNT5A and its receptor ROR2 to gastric cancer." (PMID 37722040, 2023). "Here, we show that the WNT5A coreceptor ROR2 can be transferred from CAFs to gastric cancer cells via signaling filopodia, thereby inducing JNK signaling, actin polarization, and directional migration in the receiving cell." (PMID 37722040, 2023). "Our results are supported by previous reports indicating that the ROR2 is down-regulated in gastric cancer cells." (PMID 37722040, 2023). "The spreading of the receptor can explain how gastric cancer cells, low in ROR2, can respond to a WNT5A-high microenvironment and change into an invasive phenotype." (PMID 37722040, 2023). "Here, we show that ROR2 is up-regulated on pancreatic and gastric CAFs compared to the gastric cancer cell lines and normal gastric fibroblasts." (PMID 37722040, 2023). "Surprisingly, we observe that ROR2 is transported from CAFs to gastric cancer cells via this network." (PMID 37722040, 2023). "Using various in vitro and in vivo assays, we demonstrate a promoting role of transferred ROR2 in establishing cell polarity and enhancing the invasion of gastric cancer cells." (PMID 37722040, 2023). "High-resolution microscopy revealed that filopodia tips from ROR2-overexpressed cells bud off and fuse with the plasma membrane of the receiving gastric cancer cells." (PMID 37722040, 2023). "Together with the Wnt co-receptor and cytoneme initiator Ror2, Flot2 determines the number and length of Wnt3 cytonemes in gastric cancer." (PMID 36040316, 2022). "Meanwhile, a recent study demonstrated that the activation of Wnt/Ror2 signaling in mesenchymal stem cells promotes cell proliferation of gastric cancer cells by stimulating the secretion of CXCL16." (PMID 33924999, 2021). "Activation of Ror2 signalling in the Wnt producing gastric cancer cells leads to an increase of Wnt-positive cytonemes and enhances Wnt-mediated proliferation in the neighbouring gastric cancer cells." (PMID 30255333, 2018). "Importance of ror2-dependent cytonemes in gastric cancer cell proliferation and formation of intestinal crypt cell organoids." (PMID 30060804, 2018). "It has been shown that compared to normal tissue, ROR2 is frequently downregulated in gastric carcinoma tissues, which suggests that ROR2 has a tumour suppressive role in gastric carcinoma." (PMID 29570681, 2018). "While WNT5A/ROR2 signaling acts tumor suppressive in hepatocellular carcinoma, gastric carcinoma, and myelogenous leukemia, it enhances proliferation of chronic lymphocytic leukemia." (PMID 29930766, 2018). "Ror2-mediated Wnt cytonemes also regulate the proliferation of human gastric cancer cells." (PMID 30060804, 2018). "This hypothesis is supported by recent findings showing that Wnt-Ror2-positive mesenchymal cells promote gastric cancer cell proliferation if co-cultivated." (PMID 30060804, 2018). "Why gastric cancer cells respond to this signal is still unclear, as their expression level for the central WNT5A receptor, ROR2, is very low." (PMID 37722040, 2023). "WNT5A also induced gastric cancer migration and invasion by binding to FZD2 and ROR2, and treatment in vivo with anti-WNT5A antibody inhibited liver metastasis of gastric cancer cells." (PMID 33178184, 2020). "The β-catenin-independent branch plays a similarly important role in cancer progression: the key ligands Wnt5a and Ror2 are upregulated in various gastric cancers, regardless of the histological phenotype." (PMID 30060804, 2018).
gastric cancer (continued). "In addition, we show that human gastric cancer cells AGS, which primarily express the Wnt ligand Wnt1, process paracrine Wnt signaling via cytonemes, which are influenced by Ror2 signaling." (PMID 30060804, 2018). "However, how gastric cancer cells can respond to WNT5A signaling remains unclear, given that the main receptor, ROR2, is commonly down-regulated in these cells." (PMID 37722040, 2023). "In addition, blocking WNT5A-mediated ROR2 internalization suppressed gastric cancer tumor cell invasion and metastasis in WNT5A-high but not WNT5A-low cells, suggesting a direct role for ROR2 in activating the Wnt/PCP pathway rather than a chemokine signaling pathway." (PMID 37722040, 2023).
renal cell carcinoma (11 papers, 2014 to 2025). "The effect of loss of ROR2 function was evident in renal cell carcinoma (RCC) cells." (PMID 26305508, 2015). "The upregulation of ROR2 has been established in a multitude of tumor types, such as osteosarcoma, prostate cancer, and renal cell carcinoma." (PMID 34440262, 2021). "Nevertheless, anti-ROR2 ADCs and ROR2-specific CAR-T cells are clinically evaluated in solid malignancies and in phase I/II in renal cell carcinoma, respectively." (PMID 38773263, 2024). "Two additional active clinical trials are ongoing to investigate ROR2-specific CAR T cells in ROR2-positive renal cell carcinomas (NCT03393936) and ROR2 expressing solid malignancies (NCT03960060)." (PMID 34440262, 2021). "Several early‐stage trials involving CAR T cells for renal cell carcinoma (RCC) are ongoing, assessing the feasibility of mainly two receptor tyrosine kinase targets: AXL, which plays diverse roles in tumor cell proliferation, migration, and survival (NCT03393936) and ROR2 (NCT03960060)." (PMID 35844304, 2022).
brachydactyly type B (10 papers, 2008 to 2023). A condition characterized by incomplete development (hypoplasia) or absence of the outermost bones of the fingers and toes (distal phalanges) and nails. "Mutations in Ror2 associate with human disease including Robinow and Brachydactyly type B skeletal syndroms." (PMID 30729180, 2019). "This problem has particular importance because mutations in ROR2 are associated with two human skeletal dysmorphology syndromes, recessive Robinow Syndrome (RS) and dominant acting Brachydactyly type B (BDB)." (PMID 18365018, 2008).
colorectal cancer (10 papers, 2014 to 2025). A primary or metastatic malignant neoplasm that affects the colon or rectum. "This is of relevance to our earlier analysis of colorectal adenomas and colorectal cancer where we observed a stepwise reduction in ROR2 expression from normal colon tissue, through pre-malignant ademonas through to cancer." (PMID 33494187, 2021). "Epigenetic inactivation of the ROR2 promoter has been observed in colorectal cancer where ROR2 acts as a tumour suppressor." (PMID 33494187, 2021). "We have previously identified the Wnt receptor, ROR2, as a gene of potential interest in EC, and have also shown that it can be epigenetically regulated in the development of colorectal cancer." (PMID 33494187, 2021). "In contrast, another study using quantitative real-time PCR detected a significantly higher expression of ROR2 in colorectal cancer compared with adjacent normal tissue." (PMID 33445713, 2021). "Consistent with its reported antagonism of β-catenin dependent Wnt signals, a 2010 study found ROR2 to be silenced in colorectal cancer, resulting in increased cellular proliferation." (PMID 27440078, 2016). "We also assessed the effects of altered ROR2 expression on β-catenin dependent Wnt signalling, proliferation, migration and invasion properties in colorectal cancer cells." (PMID 27440078, 2016). "Reduced ROR2 expression was found to correlate with ROR2 promoter hypermethylation in colorectal cancer cell lines, carcinomas and adenomas." (PMID 27440078, 2016). "ROR2 play a key role as an important mediator of the Wnt signaling pathway in colorectal cancer, but this gene might be involves in pathogenesis of pituitary prolactinoma through activation of Wnt signaling pathway." (PMID 33709028, 2021). "In this study, we investigated whether ROR2 expression is altered in colorectal cancers and adenomas." (PMID 27440078, 2016). "ROR2 is frequently epigenetically inactivated by promoter hypermethylation in the early stages of colorectal neoplasia and this may contribute to colorectal cancer progression by increasing cellular proliferation and migration." (PMID 27440078, 2016). "However, other reports in colorectal cancer, melanoma and osteosarcoma have found elevated ROR2 expression in tumours compared to normal tissue." (PMID 27440078, 2016). "A recent study furthermore identified PLOD2, HADH, LCOR, and REEP1 as novel target genes of the ROR2/DVL2/ATF2 pathway, which were involved in the proliferation of colorectal cancer cells." (PMID 33445713, 2021). "In colorectal cancer, HADH has been implicated in non-canonical Wnt signaling, regulating tumor proliferation and metabolic activity via the Wnt5a/b-Ror2/Dvl2-ATF2/4 axis." (PMID 40821775, 2025).
myeloma (10 papers, 2014 to 2025). "In an in vivo model, reducing ROR2 (which supports the interaction between myeloma cells and the bone marrow microenvironment) caused the cells to detach from their niche and triggered apoptosis." (PMID 40649999, 2025). "In multiple myeloma, WNT5A mediates the adhesion of myeloma cells to bone marrow cells via a ROR2 and AKT-dependent mechanism." (PMID 36982422, 2023). "ROR2 expression was also shown to activate AKT signaling in multiple myeloma, whereas PTK7 expression elicits anti-apoptotic effects in T cell acute lymphoblastic leukemia (T-ALL)." (PMID 35504983, 2022). "Similar observations have been made for ROR2: multiple myeloma cells with stable ROR2 knockdown were mostly unable to home into the bone marrow due to a defective adhesion to the bone marrow microenvironment." (PMID 33445713, 2021). "MM-MSCs and pre-OBs from myeloma patients exhibited decreased levels of Ror2, and co-culture with myeloma cells downregulated the expression of both FZD5 and Ror2, thus contributing to reduced OB differentiation." (PMID 34067236, 2021). "In multiple myeloma, ROR2 has been shown to exert a pivotal role in cancer cell adhesion; genomic studies have indicated that the pathways mostly deregulated by ROR2 are phosphatidylinositol 3-kinase (PI3K)/AKT and mTOR." (PMID 32614787, 2020). "Although Wnt5a has been reported to promote osteoblastogenesis of human MSCs through Fzd receptors and Ror2, it has been found that myeloma cells in co-culture with pre-OBs inhibit Ror2 expression in the latter, thus impairing osteogenic differentiation and contributing to OB suppression." (PMID 25268740, 2014). "Furthermore, in multiple myeloma ROR2 was recently identified by gene expression analysis and IHC to be overexpressed on plasma cells in one third of the investigated patients, suggesting that further research is warranted to clarify its role in hematological malignancies." (PMID 33445713, 2021). "Receptor Tyrosine Kinase-like Orphan Receptor 2 (ROR2), the receptor for the WNT non-canonical pathway, was found to be significantly expressed in myeloma cells by an objective evaluation of receptor tyrosine kinases overexpressed in myeloma." (PMID 40649999, 2025).
renal carcinoma (8 papers, 2010 to 2024). A carcinoma arising from the epithelium of the renal parenchyma or the renal pelvis. "It is possible that ROR2 loss affected both arms of the Wnt signalling pathways as had been previously reported in breast and renal cancer, resulting in the observed phenotypic changes." (PMID 27440078, 2016). "Overexpressing ROR2 enhances β-catenin-mediated transcription; conversely, knocking down ROR2 decreases it in renal cancer cells." (PMID 35915068, 2022). "When looking at the clinical trials registered to date, there are two additional studies investigating the ROR2-specific CAR T cells in solid malignancies expressing ROR2 (NCT03960060) or, more specifically, ROR2-positive renal carcinomas (NCT03393936)." (PMID 33445713, 2021). "In addition, ROR2 overexpression promoted renal cancer cell proliferation and activated the PI3K/AKT signaling pathway." (PMID 32614787, 2020).
cervical carcinoma (7 papers, 2011 to 2021). A carcinoma arising from either the exocervical squamous epithelium or the endocervical glandular epithelium. "A very recent paper reported that ROR2 is over-expressed in cervical cancer and associated with unfavourable prognosis and tumour progression." (PMID 26515598, 2015). "Moreover, ROR2 also showed higher expression in HPV+ cervical cancer cell lines compared to HPV− cervical cancer cell lines." (PMID 30655605, 2019). "High expression of ROR2 is upregulated in non-small cell lung cancer (NSCLC) and cervical cancer, and is also related to advanced TNM stage indicating poor prognosis." (PMID 29108281, 2017). "Interestingly, we observed overexpression of ROR2 in both HPV+ and HPV− cervical cancer cell lines." (PMID 30655605, 2019).
lung carcinoma (6 papers, 2008 to 2023). "Both ROR1 and ROR2 were found to be highly expressed in a lung cancer cell line derived from CTCs from a patient with relapsed small cell lung cancer." (PMID 33445713, 2021). "Previous studies have shown that the classical Wnt signaling pathway is mediated by Ror2 in human lung cancer cells." (PMID 31060506, 2019). "Here we report that Ror2 also positively modulates Wnt3a-activated canonical signaling in a lung carcinoma, H441 cell line." (PMID 18215320, 2008). "We aimed to determine whether receptor tyrosine kinase‐like orphan receptor 2 (ROR2) is involved in the occurrence of acute lung injury (ALI) by an animal study and explore the effect of ROR2 downregulation on lipopolysaccharide (LPS)‐treated human lung carcinoma A549 cells by a cytological study." (PMID 37102658, 2023). "The aim of the present study was to determine whether ROR2 is involved in the pathogenesis and development of ALI by an animal study and explore the effect of ROR2 downregulation on LPS‐treated human lung carcinoma A549 cells by a cytological study." (PMID 37102658, 2023).
brachydactyly (5 papers, 2017 to 2025). A disease characterized by the presence of brachydactyly, including syndromic and non-syndromic forms. "BDB1 is the most severe form of brachydactyly and is caused by truncating variants in the receptor tyrosine kinase–like orphan receptor 2 (ROR2) gene." (PMID 36064339, 2022). "Based on the close phenotypic overlap of human brachydactyly-causing mutations in ROR2 and NOG, we hypothesized that NOG may directly interact with the Wnt-5a/Ror2 pathway." (PMID 28523267, 2017). "Intriguingly, two closely related brachydactyly subtypes, BDB1 and BDB2, are caused by mutations in ROR2 or NOGGIN, respectively." (PMID 28523267, 2017).
endometrial cancer (5 papers, 2020 to 2025). Primary or metastatic malignant neoplasm involving the endometrium (mucous membrane that lines the endometrial cavity). "The aim of this study was to investigate the role of ROR2 in endometrial cancer (EC) and the potential mechanism associated with its altered expression." (PMID 33494187, 2021). "Therefore, we concluded that ROR2 plays a tumour suppressor role in endometrial cancer and appears to be a diagnostic or therapeutic candidate." (PMID 33494187, 2021). "The association between ROR2 mRNA expression levels and clinicopathological parameters, including overall survival (OS), in EC was analysed in The Cancer Genome Atlas Uterine Corpus Endometrial Carcinoma (TCGA-UCEC) cohort and GEO dataset GSE17025." (PMID 33494187, 2021). "To further investigate these findings, we analyzed the ROR2 expression in a large cohort of low-grade early-stage endometrial carcinomas (150 samples from CTNNB1 wild-type tumors and 15 from mutated counterparts)." (PMID 41227323, 2025). "The tyrosine kinase receptor ROR2 has been reported as upregulated gene in numerous types of human cancer, such as laryngeal squamous cell carcinoma, and endometrial cancer." (PMID 38565739, 2024). "In contrast, in prostate, colorectal and endometrial cancer some studies attribute a tumor suppressive function to ROR2." (PMID 33445713, 2021). "Our previous in vitro study in EC showed ROR2 overexpression in combination with silencing its sister receptor ROR1 inhibited the metastatic potential of KLE endometrial cancer cells more than either of the modifications alone." (PMID 33494187, 2021). "The aim of this study was to investigate the role of ROR2 in endometrial cancer and to determine if ROR2 expression is epigenetically regulated." (PMID 33494187, 2021). "Through the analyses of publicly available TCGA and GEO datasets, low ROR2 expression was correlated with unfavourable outcome and reduced overall survival of endometrial cancer patients." (PMID 33494187, 2021). "The effect of ROR1 and/or ROR2 modulation on cell proliferation, adhesion, migration and invasion was analysed in two endometrial cancer cell lines (KLE and MFE-296)." (PMID 32807831, 2020). "ROR1 silencing and ROR2 overexpression significantly inhibited proliferation of KLE endometrial cancer cells and decreased migration." (PMID 32807831, 2020). "The aim of this study was to investigate the role of ROR1 and ROR2 in endometrial cancer via immunohistochemistry (IHC) in a large endometrial cancer patient cohort (n = 499) and through in vitro analysis in endometrial cancer cell lines." (PMID 32807831, 2020). "In addition, we observed epigenetic repression of ROR2 expression in endometrial cancer cell lines and patient samples." (PMID 33494187, 2021). "The presumed ligand for ROR2 in endometrial cancer is Wnt5a." (PMID 33494187, 2021).
pancreatic cancer (5 papers, 2013 to 2021). "Recently, Wnt5a/Ror2 signaling has been implicated as an important pathway in epithelial-mesenchymal transition and promotion of invasion and metastasis in pancreatic cancer." (PMID 28427201, 2017). "We correlated mRNA and protein expression of ROR2 with tumour grade, stage and overall survival (OS) in three independent pancreatic cancer cohorts (ICGC-PACA-AU, TCGA-PAAD and CPTAC-PDAC)." (PMID 34763666, 2021). "We strongly recommend an independent assessment of ROR2 protein expression in a pancreatic cancer cohort to clarify this question." (PMID 34763666, 2021). "CTHRC1 has been reported to be highly expressed in pancreatic cancer and hepatocellular carcinoma, but neither the role of Ror2 or CTHRC1 has been studied in UC." (PMID 28427201, 2017). "Treatment with recombinant Wnt5a elevated the nuclear β-catenin level in pancreatic cancer cells, without altering the Ror2 expression." (PMID 24156409, 2013).